CCL2 (C-C motif chemokine ligand 2)
Diseases named in the same sentence as CCL2 in open-access papers (continued):
Sharing a sentence is not in itself a finding about the gene and the disease.
ovarian carcinoma (continued). "Thus, the CCL2/CCR2 axis represents an attractive target for ovarian cancer therapy." (PMID 30274280, 2018). "The responsible mechanisms involve a gene specific and IKKβ-dependent recruitment of S536 phosphorylated p65 NFκB to IL-8 and CCL2 promoters, suggesting that anti-inflammatory therapy targeting IKKβ might increase the BZ effectiveness in ovarian cancer treatment." (PMID 25790431, 2015). "CCL2, in turn, has not been linked with increased migration of colorectal malignancy, however, such activity of this chemokine has been reported in the case of breast and ovarian cancer cells." (PMID 26284488, 2015). "In breast and ovarian cancers, the TNF-α secreted by malignant cells potently induces CCL2/MCP-1 expression, with nearly a twofold increase upon TNF-α stimulation compared with its inhibition." (PMID 41341593, 2025). "Investigate how SLFN11 affects the response to immunotherapy by regulating immune cell infiltration (such as T cells and macrophages) or cytokine secretion (such as the CCL2/CCR2 axis), especially in hepatocellular carcinoma and ovarian cancer." (PMID 40766331, 2025). "In a cultured cell line derived from the ascites of a patient with platinum resistant ovarian cancer (ET2), elevated levels of CCL2, CCL3, CCL4, CCL5, CXCL1, CXCL8 and CXCL10 were detected in the cultured media." (PMID 41424784, 2025). "Following the bioinformatics analysis, the study explored the expression levels of CCL2, IL10, IL6, and TGFβ1 in normal ovarian epithelial cells (HOSE) and ovarian cancer cells (SKOV3)." (PMID 39981173, 2025). "We found that CCL2 and CCL4 were commonly expressed in several ovarian cancer cell lines, a patient-derived tumor cell line and patient serum samples in vitro." (PMID 41424784, 2025). "Second, the omenta of HGSC patients produced higher levels of three cytokines, namely HGF, SDF-1a/CXCL12 and MCP-1/CCL2, known to mediate cell migration, invasion, proliferation and metastasis in ovarian cancer." (PMID 40076450, 2025). "For instance, CX3CR1 was significantly correlated with CCL2/3 and (R = 0.34, P < 1.03e−09) and CX3CL1 (R = 0.18, P < .0015) in epithelial ovarian cancer." (PMID 38241595, 2024). "Macrophages produced higher amounts of CCL2 and CCL5 compared to Met5A, ovarian cancer, and IOSE80PC cells." (PMID 36766725, 2023). "For instance, the chemokine CCL2, also known as monocyte chemoattractant protein-1 (MCP-1), has been shown to promote tumor growth and angiogenesis in ovarian cancer." (PMID 37762405, 2023). "A large number of cytokines have been reported as elevated in ovarian cancer ascites samples including IL-6, IL-8, IL-10, IL-15, IP-10/CXCL10, MCP-1/CCL2, Mip1α/CCL3, Mip1β/CCL4, MDC, and VEGF." (PMID 36860657, 2023). "However, the mechanism of action of CCL2 in ovarian cancer development remains unclear." (PMID 37445830, 2023). "In this study, we demonstrated that CCL2 and CCL5 derived from macrophages induced mesothelial expression of the adhesion-related genes ITGA2 and VEGFC to increase the adhesion of ovarian cancer cells." (PMID 36766725, 2023). "Ovarian cancer patients have been found to have a higher concentration of inflammatory cytokines such as IL-6, CCL2/MCP-1, and TNF-α, which play an important role in the disease’s genesis and progression." (PMID 36386196, 2022). "Exploration of this phenotypic shift found that cross-linking of MOv18 IgE on human monocytes by ovarian cancer cells, induced a pro-inflammatory secretome (TNF-α, CCL2, IL-10, CXCL-10, IL-1β, IL-6, and IL-23)." (PMID 35020853, 2022). "mAbs targeted against CCL2 and CSF-1R to reduce TAM recruitment and/or survival have been investigated in phase I clinical trials involving ovarian cancer patients (NCT02526017)." (PMID 35020853, 2022). "Ovarian cancer cells secrete transforming growth factor (TGF-β) and act on human peritoneal mesothelial cells to secrete CCL2 and induce their own activation via the p38/MAPK pathway." (PMID 34445235, 2021).
ovarian carcinoma (continued). "Meanwhile, the chemokine landscape of ovarian cancer was found to be quite heterogeneous, because of different functions of known lymphocyte-recruiting chemokines in TME, such as CCL2, CXCL9, CXCL10, CXCL12, and CXCL16." (PMID 34386037, 2021). "We went back to the analysis of TCGA datasets of human GBM and ovarian cancer and observed a significantly positive correlation between LIF and CCL2, CD163, and CD206 in both tumor types." (PMID 31186412, 2019). "Targeting of these cells with anti-CCL2 antibody, anti-CSF-IR inhibitors, anti-CD52 antibody, and anti-CD11b antibody for therapy of ovarian cancer has been investigated in preclinical models of ovarian cancer." (PMID 30200478, 2018). "The number of TAMs is positively regulated by CCL2/MCP-1, which is released from ovarian cancer cells into the ascites." (PMID 28275576, 2017). "In in vivo solid tumor models (breast, gastric and ovarian cancers), it was shown that CCL2/CCR2 axis mediated the migration of MSC into the tumor and also showed evidence of CCL2-mediated protumor effect." (PMID 28045930, 2017). "The underlying mechanisms likely involve the NFκB-regulated chemokine expression, since several studies have demonstrated that the expression of CCL2, CXCL1, CXCL2, and IL-8/CXCL8 is mediated by NFκB in ovarian cancer cells." (PMID 25790431, 2015). "We demonstrate here that CCL2 is expressed in normal human ovarian surface epithelium (HOSE) cells and is silenced in most ovarian cancer cell lines, and silenced or downregulated in the majority of primary ovarian adenocarcinomas." (PMID 15900302, 2005). "Having demonstrated that CCL2 is strongly expressed in cultured and uncultured HOSE cells, and that expression is lost or reduced in the vast majority of ovarian cancer cell lines, we next investigated its expression in primary ovarian tumours." (PMID 15900302, 2005). "The expression of CCL2 mRNA was next examined in a larger panel of HOSE and ovarian cancer cell lines by Northern blot analysis." (PMID 15900302, 2005). "Expression of CCL2 was detected at similar levels in the HOSE17.1 cell line, the uncultured normal OSE cells, and the PEO14 and 27/87 ovarian cancer cell lines." (PMID 15900302, 2005). "On the pro-tumor side, CCL2 (MCP-1), a potent monocyte chemoattractant, is correlated with poor overall survival and contributes to ovarian cancer progression through recruitment of M2 macrophages, promotion of tumor metastasis, and promotion of chemotherapy resistance." (PMID 40689422, 2025). "However, levels of CCL2 and CCL4 were significantly increased in patients with ovarian cancer compared to healthy donors." (PMID 41424784, 2025). "Using female healthy donors with no history of ovarian cancer, we were also able to detect levels of CCL2, CCL4, CCL5, CXCL10 and CXCL12." (PMID 41424784, 2025). "Examples of CCL2/CCR2 axis antagonists undergoing early phase clinical trials include trabectedin, a CCL2 antagonist used to treat ovarian cancer, and cenicriviroc, a CCR2 (and CCR5) inhibitor currently progressing through clinical trials for MASH and fibrosis." (PMID 39684877, 2024). "Some studies had found that ETS1 exosomes secreted by ovarian cancer cells induce the polarization of M2 macrophages, which overexpress CD163, IL-10, CCL2, CXCL5 and other immunosuppressive factors, and significantly stimulate the migration of ovarian cancer cells." (PMID 39539540, 2024). "We found that ovarian cancer cells treated with carboplatin in combination with CCL2/MCP-1 for 48 hours had increased SOX2, OCT4, and NANOG gene expression and greater spheroid formation ability relative to carboplatin or CCL2/MCP-1 treatment alone." (PMID 39287565, 2024). "Also in ovarian cancer, CAF secrete other secretory factors, including VEGF, IL-6, granulocyte colony-stimulating factor (G-CSF), CCL2/MCP-1, and CXCL8/IL-8, which are involved in tumorigenesis and lead to cancerous tumor growth." (PMID 37108425, 2023).
ovarian carcinoma (continued). "In addition to affecting differentiation, TME-derived chemokines can recruit MDSCs to infiltrate into the tumor microenvironment, such as CCL2, CCL5, and other chemokines secreted by breast, gastric, and ovarian cancers." (PMID 37801479, 2023). "There are also some reports regarding the potential roles of CCL2 and CCL5 in ovarian cancer." (PMID 36766725, 2023). "Taken together, these data indicated that CCL2 and CCL5 secreted by macrophages can increase the expression of adhesion-related genes ITGA2 and VEGFC via the JNK and Akt pathways in Met5A cells, resulting in enhanced ovarian cancer-mesothelial cell adhesion." (PMID 36766725, 2023). "Furthermore, increased production of CC chemokine ligand 2 (CCL2) and CCL5 by macrophages elevated ovarian cancer-mesothelial cell adhesion." (PMID 36766725, 2023). "In ovarian cancer, both CXCL5 and CCL2 are pro-metastatic cytokines." (PMID 36477408, 2022). "Regarding the upregulation of MCP-1/CCL2 in response to a high oxicam dose and longer exposure, the expression of MCP-1 has been shown to be upregulated several-fold in ovarian cancer by chemotherapy, and the effect has been reproducible at the mRNA and protein levels, both in vitro and in vivo." (PMID 34885960, 2021). "Chemotherapy with paclitaxel or carboplatin may generate debris in ID8 ovarian cancer cells which triggers macrophage production of the proinflammatory cytokines TNF-α, MIP-2/CXCL2, MIP-1β/CCL4, CCL2/MCP-1, as well as sICAM-1/CD54 and G-CSF." (PMID 33194645, 2020). "In addition, CCL2 and CCL5 have been detected by cytokine array in the supernatant of stromal cells promoting the resistant phonotype of ovarian cancer cell lines." (PMID 31990955, 2020). "Although the detailed mechanism is not clarified, CCL2 promotes invasion and adhesion of human ovarian cancer cells, and CCL2 blockade can enhance the cytotoxic effect of paclitaxel and carboplatin therapies in ovarian cancer." (PMID 33297571, 2020). "In this model, the upregulation of CCL2 and CCL5 could explain the increase in TILs, as CCL2 can induce TILs in ovarian cancer." (PMID 30487462, 2018). "We have recently shown that BZ increases expression of IL-8 and CCL2 in ovarian cancer cells, while it does not affect expression of other NFκB-dependent genes." (PMID 25790431, 2015). "ID8 ovarian carcinoma-conditioned BMDMs demonstrated a modest increase in TNFα and CCL2 following LPS stimulation, although this effect was not statistically significant." (PMID 26177198, 2015). "Therefore, targeting the CCL2/CCR2 axis could inhibit macrophage chemotaxis, potentially improving paclitaxel sensitivity in ovarian cancer patients." (PMID 38341519, 2024). "Although CCL2/MCP-1 induces recruitment of monocytes, which may support CSCs in currently unidentified ways, IL1β is a known inducer of stemness in other cancers and may also be important in ovarian cancer." (PMID 39287565, 2024). "Taken together, these results suggest that CCL2/5 can originate from noncancerous cells such as macrophages in the ovarian cancer microenvironment, as well as tumor cells, and may play a role in ovarian cancer progression and chemoresistance." (PMID 36766725, 2023). "Furthermore, CCL-2 activates the P38-MAPK pathway in cancer cells, and high expression of the CCL-2 receptor CCR-2 has been shown to be a prognostic marker for overall and progression-free survival in ovarian cancer." (PMID 37545408, 2023). "Compared with control exosomes, exosomes derived from ETS1-overexpressing ovarian cancer cells (LV-ETS1 Exos) stimulated the polarization of more macrophages toward the M2 phenotype (CD163 marker), as well as the production of more CXCL5 and CCL2 in macrophages, via integrin αvβ5/AKT/Sp1 signaling." (PMID 36477408, 2022).
ovarian carcinoma (continued). "For instance, trabectedin, which has been used to treat human ovarian cancer and myxoid liposarcoma in clinic, mechanistically acts by blocking macrophage recruitment through the targeting of monocyte chemoattractant protein‐1 (MCP‐1/CCL2), which correlates with increased macrophage infiltration." (PMID 32452100, 2020). "Some of these pro-inflammatory molecules including CCL2/MCP-1, CCL5/RANTES and IL-8 are activated during cyclical ovulation; thus, the incessant ovulation theory suggests that inflammation along with other physiological conditions enhances the progression of ovarian cancer." (PMID 30914056, 2019). "Inhibition of the CCL2/CCR2 axis using a CCR2 inhibitor significantly increased paclitaxel sensitivity in both in vitro and in vivo models, suggesting that targeting this signaling pathway could be a promising therapeutic strategy to overcome chemoresistance in ovarian cancer." (PMID 40330466, 2025). "Macrophages isolated from both the ascitic fluid and solid tumor from ovarian cancer patients exhibited very low levels of CCR2 mRNA, which correlated with the lack of chemotactic response to CCL2." (PMID 24384839, 2013).
Hyperglycemia (134 papers, 2009 to 2026). An increased concentration of glucose in the blood. "In PDR, the inflammatory milieu mediated by an increase in ECM production, chemokines such as C-C motif chemokine ligand 2 (CCL2) and hyperglycemia together increase the susceptibility of FVM formation." (PMID 37426784, 2023). "In conclusion, this study investigated the association of CTRP3, CTRP9 and MCP-1/CCL2 with hyperglycemia and the risk of development of CAD." (PMID 30557342, 2018). "Hyperglycemia was associated with (i) CCL2 chemokine induction at P6, (ii) a significant recruitment of inflammatory macrophages and an increase in total number of Iba+ macrophages/microglia cells in the inner nuclear layer (INL), and (iii) excessive apoptosis in the INL." (PMID 24278148, 2013). "Hyperglycemia leads to an enhanced expression of chemokines in kidney tissue, such as CCL2, CCL3, CCL4, CCL5, and CXCL12, involving in immune cell recruitment and modulating the inflammation." (PMID 40046045, 2025). "Second, we used the ELISA method to assess the secretion of CCL2, a vascular damage marker, and discovered that CCL2 expression was raised in HUVECs treated with hyperglycemia and senescence, while high glucose increased CCL2 expression in aging HUVECs." (PMID 38540749, 2024). "Examining each NCD individually, there was a significant interaction between LLV and CCL2/MCP‐1 in the association with elevated BP and hyperglycaemia." (PMID 39189824, 2024). "Our results show that the pancreatic β-cell model of Wolfram syndrome under hyperglycemia expresses a higher level of Ccl2 mRNA compared to the wild-type cells." (PMID 35399956, 2022). "For example, hyperglycemia can stimulate the secretion of CCL2, CCL5, and CXCL12, through podocytes and tubular cells, as reported in mouse models and DN patients, which contributes to proteinuria and glomerulosclerosis." (PMID 34221188, 2021). "Real-time PCR demonstrated that ARPE-19 cells responded to either cytokines or hyperglycemia by upregulating proinflammatory genes such as cytokines (IL-1β and IL-6) and chemokines (CCL2, CCL5) as well as VEGF, an established inducer of vascular leakage." (PMID 31344857, 2019). "CCL2/MCP-1 influences vascular inflammation via activating and recruiting leukocytes during hyperglycemia in various retinal cells (e.g., pigmented epithelial cells, Muller’s glial cells, retinal vascular endothelial cells)." (PMID 30233418, 2018). "A significant increase in CCL2 expression in adipose tissue in an experimental study significantly reduced the ability of insulin to stimulate glucose transport into cells, which led to hyperglycemia and an increase in LDL and triglyceride levels." (PMID 40943138, 2025). "In addition, morphological signs of microglial response to hyperglycemia, as well as increased pro-inflammatory mediators, such as IL-1β, CCL2 and TNF-α, were described." (PMID 36869375, 2023). "In addition, hyperglycaemia has been shown to increase the expression of monocyte chemoattractant protein-1 (MCP-1/CCL2) and VEGF by vascular endothelial cells and in the vitreous samples from patients with DR." (PMID 34359853, 2021). "In addition to the phenotypic changes, we also evaluated the bio-functional response in hyperglycemia-exposed macrophages by measuring secretion of critical proinflammatory proteins, such as IL-1β and MCP-1 (CCL2)." (PMID 32806763, 2020). "Finally, Ccl2, Tnfα and Il-1β overexpression reflects the pro-inflammatory environment induced by the hyperglycemia." (PMID 24278148, 2013). "Furthermore, stimulation with both rIL-17 and high glucose was more effective in increasing the expression of inflammatory cytokines IL-6 and TNFα and the chemokine CCL2 than either condition alone, suggesting IL-17 and hyperglycaemia synergistically promote diabetic podocyte injury." (PMID 30783187, 2019).
Hyperglycemia (continued). "β-Cells are capable of producing chemokines (e.g., MCP1/CCL2) in the presence of high FFA levels, and hyperglycemia forces β-cells to produce islet amyloid polypeptide (IAPP)." (PMID 28168202, 2017). "In fact, regulation of both, CCL2 and EGR2 mRNA expression, by higher concentrations of glucose was previously demonstrated on the model of THP1 macrophages and on PBMC in newly diagnosed pediatric patients with T1DM and T2DM suffering from hyperglycaemia." (PMID 33658980, 2020). "Moreover, in vitro hyperglycemia induced TLR-4 expression via PKC leading to increased levels of IL-6 and chemokine (CC motif) chemokine ligand 2 (CCL-2), via IkB/NF-kB pathway." (PMID 31835864, 2019). "Lastly, a significant decrease in the expression of IL-6, TNF-α, and CCL2 was noted in the cornea at 7 days after hyperglycemia, whereas no significant alterations in the expression of these genes could be noted at 14 or 28 days of hyperglycemia." (PMID 39749321, 2024). "To test this hypothesis, we quantified the gene expression of macrophage-secreted cytokines (IL-1β, IL-6, TNF-α, IL-10) and chemokines (CCL2) in the lacrimal gland, conjunctiva and cornea of non-diabetic normoglycemic mice and diabetic mice with 7, 14, and 28 days of hyperglycemia." (PMID 39749321, 2024). "Thus, the dysregulation of CCL2 expression in FDR could contribute to the increased infiltration of CD206 negative monocytes/macrophages into adipose tissue, which we observed previously in response to experimental hyperglycaemia in obese women." (PMID 33658980, 2020). "HSCs but not hepatocytes or LSEC showed higher CCL2 expression (which is the ligand with the highest affinity for CCR2) in STZ-induced diabetic mice, suggesting the possible migration of CCR2+ Tregs into the hyperglycemia-induced inflamed liver." (PMID 27464894, 2016).